KLF5 (KLF transcription factor 5)
Diseases named in the same sentence as KLF5 in open-access papers (continued):
Sharing a sentence is not in itself a finding about the gene and the disease.
tumor (continued). "From an immune response perspective, KLF5 negatively correlates with B-cell naïve, CD8+ T cells, and macrophage MO cells, suggesting that overexpression in the tumor microenvironment inhibits the immune system’s ability to fight cancer." (PMID 37239940, 2023). "Immunoblotting of transplanted tumor tissues from BALB/C-nude mice indicated that DCC-2036 significantly inhibited p-AXL, AXL, and KLF5." (PMID 36042208, 2022). "Our previous study demonstrated that the KLF5 transcription factor promotes BLBC cell proliferation and tumor growth." (PMID 35342356, 2022). "Knock-down of KDM3A, KLF5, SMAD4 or EGFR in tumour cells influenced the immune TME and re-sensitized tumours to combination immunotherapy." (PMID 33671588, 2021). "UALCAN was used to compare the effects of different drinking frequencies for tumor patients on the expression levels of KLF4 and KLF5 in ESCA." (PMID 34367275, 2021). "Thus, our results indicated that KLF5 could be an important suppressor of tumor invasion and metastasis of PCa because KLF5 deletion/downregulation could promote the expression of a tumor cell autocrine cytokine and the subsequent cell signaling to enhance PCa cell invasive ability." (PMID 32546700, 2020). "FBXW7 is considered as a potent tumor suppressor as most of its target substrates can function as potential growth promoters, including c-Myc, Notch, cyclin E, c-JUN, and KLF5." (PMID 30791487, 2019). "Subsequently, we observed marked increase of KLF5, GCN5, and GDF15 expression in 185 NSCLC tumor tissues by immunohistochemical (IHC) staining." (PMID 29773900, 2018). "In this study, we not only examined the levels of KLF5, GCN5, GDF15, C5aR, or C5a in NSCLC samples, but also evaluated the roles of KLF5, GCN5 and GDF15 in C5a-triggered cell proliferation in vitro and xenograft tumor growth in vivo." (PMID 29773900, 2018). "On the other hand, it can repress another transcription factor, Krüppel-like factor 5 (KLF5), the presence of which can promote SMAD2/3 pathway leading to tumor progression." (PMID 29254283, 2017). "The upregulated gene set also included known genes related to pluripotency and growth, such as KLF5, FGF4 and GDF3, and 8 downregulated genes were known tumor suppressors." (PMID 28837588, 2017). "Finally, we tested whether BAP1 promoted HCC1806 tumour growth through KLF5." (PMID 26419610, 2015). "To test whether Klf5 deletion plays a role in tumor angiogenesis, we first examined H&E stained tissue sections for the number of intraepithelial blood vessels, indicated by histological appearance and the presence of red blood cells between wildtype tissues and those with Klf5 deletion." (PMID 25896712, 2015). "For example, KLF family proteins have been shown to have either a tumor-promoting (KLF4, KLF6, KLF9, KLF10, KLF11, and KLF17) or a tumor-suppressing (KLF5, KLF12) role by intervening in cell signaling associated with proliferation and/or suppression." (PMID 26320172, 2015). "Next, we want to confirm the inhibitory effects of curcumin on tumor growth and the YAP/KLF5/cyclin D1 axis in a nude mice xenograft model." (PMID 25170806, 2014). "A xenograft assay in nude mice finally proved the potent inhibitory effects of curcumin on tumor growth and the pro-proliferative YAP/TAZ/KLF5/cyclin D1 axis." (PMID 25170806, 2014). "Additionally, the clinicopathological features of patients with KLF5 overexpression were TNM stage, tumor size, alpha fetoprotein (AFP) level, portal vein thrombosis, and HBV infection." (PMID 40697993, 2025). "In addition, decreased expression of KLF5 (cancer stage II), KLHL13 (stages III and IV), and CUL3 (stages II and IV) correlated with advanced tumor staging." (PMID 41443421, 2025). "KLF5 is upregulated in PDAC, and its downregulation was reported to inhibit PDAC cell proliferation and tumorigenesis in mice by increasing the expression of the tumor suppressor NDRG2 and reducing the activation of STAT5." (PMID 39972489, 2025).
tumor (continued). "Through a comprehensive workflow combining H3K27ac-ChIP-seq and RNA-seq analyses, we identified critical TFs and tumor-specific super-enhancer domains (T-SEDs) that regulate gene expression in HPV+ HNSCC, such as TP63, SMAD3, FOSL2, JUND, JUNB, KLF5, and TFAP2A." (PMID 41323280, 2025). "PC3-ML cells contain high levels of exosomal miR-888, which downregulates proteins such as Krüppel-like factor 5 (KLF5), retinoblastoma-like protein 1 (RBL1), tissue Inhibitor of metalloproteinases 2 (TIMP2), and SMAD family member 4 (SMAD4), strengthening tumour cell abilities." (PMID 41465110, 2025). "Enriched in PC3-ML cells, exosomal miR-888 downregulates important proteins such as Krüppel-like factor 5 (KLF5), retinoblastoma-like protein 1 (RBL1), tissue Inhibitor of metalloproteinases 2 (TIMP2), and SMAD family member 4 (SMAD4), enhancing overall tumor cell capabilities." (PMID 40556678, 2025). "Tumour formation under irradiation in vivo was simulated after the sh‐NEDD4L and sh‐KLF5 were delivered to the mice, showing that NEDD4L inhibition accelerated the rate of ESCC tumour generation, while KLF5 inhibition conversely suppressed tumour growth." (PMID 39317954, 2024). "Changes in tumour resistance to radiation were analysed in mice underexpressing NEDD4L and KLF5." (PMID 39317954, 2024). "Klf5 deacetylation amplifies the FGF/TNF signaling interplay between iCAFs and tumor cells." (PMID 38781024, 2024). "Consistent with our earlier observations about the NRF2/KLF5/SLC1A5 pathway in cultured cells, immunoblotting of the MT-101 tumor tissues showed that the accumulation of NRF2, KLF5, and SLC1A5 was obviously reduced upon CsA treatment and upon the CsA and CB-839 combination treatment." (PMID 38830868, 2024). "More importantly, EPI and DDP showed no significant therapeutic effects on the KLF5-overexpressing tumors, whereas both drugs significantly suppressed tumor growth in the control group." (PMID 37588224, 2024). "In PCa bone metastasis, ac-KLF5 (acetylated KLF5) up-regulates CXCR4 expression through histone acetylation in the promoter region of CXCR4 gene, and further promotes IL-11 secretion, osteoclast differentiation and the regulation of tumor cell plasticity." (PMID 37190171, 2023). "To evaluate whether Klf5 alters the tumor-immune microenvironment, we performed RNA-sequence analysis on tumor tissues from EMT6 or 67NR mouse tumor models." (PMID 36923542, 2023). "Similarly, KLF5 mediates CXCL12 expression, creating an immunosuppressive microenvironment in tumor tissue and thus reducing the efficacy of immunotherapy." (PMID 36761967, 2023). "Genetic ablation of Klf5, FZU00,004 (a KLF5 inhibitor) and CEL failed to reduce the frequency of tumor-infiltrating Tregs (Cd4+Cd25+Foxp3+ T cells), but Klf5 depletion increased the number of Cd3+Cd8+ T cells and increased the Cd3+Cd8+/Treg ratio." (PMID 36923542, 2023). "KLF5 enhances the phosphorylation of the mammalian target of the rapamycin (mTOR) via the activation of PI3K/AKT signaling, thereby inhibiting autophagy in melanoma cells and enhancing tumor cell survival." (PMID 36761967, 2023). "We first successfully constructed PDOs derived from tumor tissues of CRC patients in vitro and conducted a drug screening assay to find that ML264, a KLF5 inhibitor, could restore oxaliplatin sensitivity in CRC PDOs." (PMID 35379798, 2022). "These lines of evidence support the hypothesis that the KLF5 protein expression level and SMAD4 status could be possible biomarkers, which are predictive of tumor sensitivity to h4#147D." (PMID 36385956, 2022). "Thus, YAP and TAZ exert tumor promotion in part via blocking KLF5 from WWP1-involved degradation and stabilizing KLF5 activity." (PMID 34226507, 2021). "Indeed, Ac-KLF5 transactivates the CXCL12/CXCR4 chemokine axis, IL-11 cytokine signaling, and likely other paracrine molecules in tumor cells, as revealed by RNA-Seq, ChIP-Seq, and related analyses." (PMID 33731701, 2021).
tumor (continued). "This reciprocal relationship persists in localized prostate cancer, where KLF5 expression is low/absent and tumor cells have an AR-positive luminal identity." (PMID 34737261, 2021). "Moreover, cells with KLF5 or KLF5KQ induced larger tumor areas in the bone than those with KLF5–/– or KLF5KR, as indicated by H&E staining of bones with tumors and quantitative analyses of tumor areas." (PMID 33731701, 2021). "To further address the roles of KLF5 and its acetylation in autonomous cell proliferation rate and tumor growth in a non-bone environment, we assessed tumor sphere formation in vitro and subcutaneous tumor formation in vivo." (PMID 33731701, 2021). "RAS activation inhibits TGF-β-induced KLF5 acetylation, and the deacetylation state of KLF5 may be an important mechanism, by which KLF5 and HDAC promote cell proliferation and tumor growth." (PMID 34367275, 2021). "Sphere formation and tumor formation were both minimal with PCa cells lacking KLF5, and were rescued by the restoration of KLF5 regardless of acetylation status." (PMID 33731701, 2021). "Furthermore, the ACP samples were subjected to immunohistochemistry analysis, which demonstrated strong staining of KLF5 and E2F2 in the whole tumor tissues, especially in the cystic wall." (PMID 35155179, 2021). "Together, our study uncovered the oncogenic role of KLF5-dependent lncRNA DANCR transcription in GC in vivo and in vitro, which implicates the miR-194/AKT2 axis in tumor growth regulation, and it may be a potential therapeutic target for human GC." (PMID 34548487, 2021). "In addition, we validated (i) the co-regulatory feedback loop between SREBF1/TP63/KLF5, and (ii) canonical target genes of SREBF1 in fatty-acid metabolism (e.g., ACLY, FASN, and SCD) in xenograft tumor samples." (PMID 34272396, 2021). "This miRNA suppressed CSC properties, possessed various anti-tumour effects against CRC cell lines and CRC cell cultures derived from clinical CRC samples through direct inhibition of KLF5 and MDM2, and provoked G1 arrest via direct inhibition of TFDP1, which forms a heterodimer with E2F1." (PMID 32066912, 2020). "In summary, we found that KLF5 deletion/downregulation in PCa could promote tumor invasion and metastasis through modulating the cytokine IGF1, expressed by tumor cells, and the subsequent cell signaling." (PMID 32546700, 2020). "Furthermore, KLF5 and AR interacted with each other to regulate transcription of AR target genes (e.g., MYC, CCND1, and PSA) to promote cell proliferation and tumor growth." (PMID 32245249, 2020). "This process does not occur randomly due to the fact that hotspot genes with an increased frequency of integration sites was identified in independent studies (i.e., tumor-suppressive fragile histidine triad gene—FHIT, or transcriptional factor Kruppel-like factor 5—KLF5)." (PMID 33203149, 2020). "Immunohistochemistry of tumor samples displays a range of positive and negative staining in the cytoplasm for PrPC, FOXO3a, and KLF5." (PMID 30478887, 2019). "On the other hand, KLF5 knockdown did not change tumor weights between the CW22RV1/shKLF5 (KLF5-KD) group: 431.25 ± 75.68 mg, n = 9 and CW22RV1/shNC (NC) group: 421.25 ± 118.74 mg, n = 9 in nude mice treated with DMSO." (PMID 31534497, 2019). "Besides, GCN5, KLF5, or GDF15 silence reduced cell proliferation in vitro and xenograft tumor growth in vivo." (PMID 29773900, 2018). "KLF5 function could be context-dependent, including a role in TTK-mediated EMT due to specific cell signaling, tumor microenvironment, and the subtype of TNBCs." (PMID 30206215, 2018).
tumor (continued). "Recently, researches have confirmed that KLF5 and GCN5 are overexpressed in many cancers, and could regulate tumor biological processes as a transcription factor and a transcriptional co-activator respectively." (PMID 29773900, 2018). "We also discovered that KLF5, GCN5, GDF15, and C5aR expression was closely correlated with the tumor size, lymph node metastasis, and TNM stage of NSCLC, indicating that these proteins may have an important function in NSCLC tumorigenesis." (PMID 29773900, 2018). "We identified seven oncogenes (NRAS, EGFR, RXRA, HRAS, KRAS, AKT1, ERBB2; q<0.10) and seven putative tumor suppressor genes (ARID1A, TXNIP, CTNNB1, PIK3RI, CDKN2A, KLF5, STAG2; q<0.10) significantly regulated between tumor and control, which were formerly reported to be altered in BC." (PMID 30419021, 2018). "In the absence of KLF5, the same SMAD2/3 pathway can cause PDAC cell apoptosis, which can repress tumor development." (PMID 29254283, 2017). "Thus TEAD4 and KLF5, in collaboration, promoted TNBC cell proliferation and tumor growth in part by inhibiting p27 gene transcription." (PMID 25970772, 2015). "Thirdly, at the molecular level Klf5 deletion significantly elevated the expression of HIF1α and its pro-angiogenic functional effectors such as VEGF and PDGF, which represent the most potent inducers of tumor angiogenesis." (PMID 25896712, 2015). "Additionally, YAP and TAZ, two effectors of the Hippo tumor suppressor pathway, can inhibit WWP1–KLF5 protein interaction and stabilize KLF5." (PMID 25170806, 2014). "Lack of a neoplastic phenotype however, does not disapprove a tumor suppressor function of Klf5, because malignant transformation often requires multiple genetic alterations and knockout of Klf5 alone is most likely insufficient for tumor induction." (PMID 23755247, 2013). "In the mouse prostate, although hemizygous deletion of Klf5 increased cell proliferation and induced hyperplasia, which is consistent with a tumor suppressor activity, no neoplasia was detected." (PMID 23755247, 2013). "Tumor tissues displayed higher levels of both Klf5 and β-catenin, irrespective of the mouse genotype from which tumors were derived." (PMID 20298593, 2010). "Moreover, we were able to significantly reduce tumor burden and size in the compound ApcMin/KRASV12 mice by reducing expression of Klf5 with genetic means." (PMID 20298593, 2010). "Given that Klf4 and Klf5 have context dependent roles, it is not surprising that Klf4 and Klf5 possess both tumor suppressor and oncogenic functions." (PMID 20514221, 2009). "Moreover, we find that the KLF5 cistrome is significantly remodeled when comparing classical and basal-like PDAC models, which is likely to account for its divergent functions across tumor states." (PMID 41241675, 2025). "Interestingly, in vivo experiments, ML264 treatment did not lead to a significant reduction in KLF5 protein levels in tumor tissues, despite its clear inhibitory effects on tumor growth and PARPi resistance." (PMID 40307891, 2025). "However, in Smad4-negative cancer cells, KLF5 is not downregulated by TGF-β, and KLF5 and Sox4 cooperate to support tumor-initiating cells, thereby facilitating tumor progression." (PMID 38569937, 2024). "Finally, we detected Cox2 expression and Cd8+ T-cell infiltration in mice inoculated with control or Klf5 KD tumor cells in the presence or absence of CEL." (PMID 36923542, 2023). "Furthermore, inhibition of KLF5 by mifepristone and its derivatives 22-24, metformin 25, mithramycin A 26, super-enhancer inhibitors 27, and the protein arginine N-methyltransferase 5 (PRMT5) inhibitor, PJ-68 28, suppress BLBC stemness and tumor growth." (PMID 35342356, 2022). "Interestingly, four tumor samples harbor duplications of only the enhancer region without the SOX2 gene, reminiscent of our previous findings regarding duplications of MYC and KLF5 enhancers." (PMID 34880227, 2021).
tumor (continued). "Importantly, Dex failed to promote cancer cell survival and tumor growth when KLF5 induction was blocked." (PMID 28030791, 2017). "Significant differences in tumour size, histological type, invasion depth, nodal metastasis status, pathological grade, Union for International Cancer Control (UICC) stage and disease-free survival outcomes were detected between the two KLF5 groups and TNFRSF11a groups (P < 0.05)." (PMID 29146991, 2017). "In our recent study, we found that deletion of Klf5 in Pten-null mouse prostates resulted in larger tumors without lumens and necrosis, which were present in tumors induced by Pten deletion alone but with enhanced activation of AKT and ERK, which are reported to promote tumor angiogenesis." (PMID 25896712, 2015). "In addition, an analysis of a genome-scale shRNA screen of 501 cancer cell lines, revealed that five non-BCR-ABL B-ALL cell lines are not enriched for a dependency on KLF5, indicating that KLF5 does not score as an oncogenic- or tumor suppressor-dependency for non-BCR-ABL B-ALL." (PMID 30038712, 2018). "Expression profiles of these transcription factors in the TCGA mRNA expression dataset for HNC showed that unlike KLF5, SP1 was significantly upregulated in tumor vs. normal patient data." (PMID 40810390, 2025). "Kruppel‐like factor 5 (KLF5) targets were enriched in the Luminal A and B, as well as HER2‐enriched subtypes, but not in Basal‐like tumours." (PMID 35182081, 2022). "When KLF5 is absent or severely downregulated, TGF-β acts as a tumor suppressor by inducing lethal EMT." (PMID 33731701, 2021).